CD34 (CD34 molecule)
Diseases named in the same sentence as CD34 in open-access papers (continued):
Sharing a sentence is not in itself a finding about the gene and the disease.
tumor (continued). "LAIR-1 was multiplexed with lymphocyte markers (CD45RA, CD4, CD8, CD20, CD56), myeloid monocyte markers (CD14, CD68, CD163 for macrophages and CD66b for neutrophils), fibroblast marker (SMA), hematopoietic progenitor cells (HPC, CD34) and tumor marker (pan CK)." (PMID 36960400, 2023). "Using a CD34+ humanized tumor mouse model, we could demonstrate that oncolytic measles viruses encoding s4-1BBL-TriXVIII significantly reduced tumor burden, whereas control measles viruses were not effective." (PMID 37310433, 2023). "CD34 extravascular positivity was observed in the tumor cells of 2/10 cases." (PMID 37349135, 2023). "For example, in gastric cancer, inhibition of the miR-665/MAPK1 signaling pathway not only reduces the expression of drug pumps, but also decreases the secretion of inflammatory factors like CD34 in the tumor microenvironment, thereby increasing the sensitivity of tumor cells to antitumor drugs." (PMID 37894282, 2023). "Moreover, patients with higher expression levels of CD31, CD34, and rCBV had a worse prognosis, indicating a link between increased angiogenesis and more aggressive tumor behavior." (PMID 38089632, 2023). "Unexpectedly, we also observed the presence of ERG-positive and CD34-negative spheroid-associated tumor cells." (PMID 37830603, 2023). "A CD34+ humanized mouse tumor model was used to evaluate whether TMV-110 can augment anti-tumor immunity in vivo." (PMID 37310433, 2023). "•The perfusion measurements were supported by CD34 staining of tumour specimens." (PMID 36718357, 2023). "In contrast, when humanized mice are developed by xenotransplantation of irradiated mice with human CD34+ stem cells to allow for the growth of human tumor tissue in the context of a humanized immune system, it is possible to evaluate the response to both targeted therapy and immune therapy." (PMID 37509357, 2023). "However, caution must be taken in the event of negative staining results: of 70 GBMS, one case was stained only with CD34, and two tumours stained only with SOX11." (PMID 37568909, 2023). "The tumor cells stained positive for CD34 and smooth muscle actin." (PMID 38065911, 2023). "CD34 may be used as marker for tumor blood vessels when the pathologist needs vascular invasion confirmation." (PMID 37568639, 2023). "However, SCGFβ is incompletely understood and has mostly been studied in the context of stem cell therapy as a direct measure of CD34+ cells and as a growth factor in tumor cells." (PMID 37202439, 2023). "Single IHC for CD34 revealed that positive cell density dramatically decreased from normal to malignant tissue, remaining positive in tumor vessels’ endothelium and a few CAFs in scattered areas in between tumor cells." (PMID 37568639, 2023). "In addition to using the CD34+/CD38 phenotype to identify CSC-like cells, we also examined the effect of NK3.3EVs on the expression of genes associated with CSC-like cells and tumor progression." (PMID 38201518, 2023). "Immunohistochemically, the tumor cells were positive for CD34 and STAT6." (PMID 37315497, 2023). "Staining of tumor tissue for CD34-MVD revealed the tumor neovascularization process." (PMID 37438780, 2023). "Single CD34 immunohistochemistry on supplemental slides quantified tumor stroma CD34_CAFs." (PMID 37568639, 2023). "With serial sections of CRLM biopsies, we defined 7–9 days post-injection as the critical period for tumor neovascularization, which was initiated from the innate liver vessels via vessel cooption and extended by vascular mimicry and thereof growth of CD34+cells." (PMID 36781833, 2023). "Of 223 HIS mice engrafted with human CD34+ hematopoietic stem and progenitor cells (HSPCs) from 27 different donors and implanted with HT-29 tumors, 76 (34%) rejected the tumors, 40 (18%) showed tumor regression, and 107 (48%) showed tumor progression." (PMID 37185301, 2023). "By contrast, CD34 staining was significantly increased in normal tissue versus tumour." (PMID 36922590, 2023).
tumor (continued). "Oncolytic measles viruses encoding s4-1BBL-TriXVIII significantly reduced tumor burden in a CD34+ humanized mouse model, whereas measles viruses lacking s4-1BBL-TriXVIII were not effective." (PMID 37310433, 2023). "The tumor cells characteristically show positivity for CD34 immunohistochemical stain." (PMID 38073992, 2023). "Furthermore, IHC analysis confirmed the upregulation of CD31 and CD34 expression in tumor tissues derived from L1‐overexpressing U87 xenograft‐bearing BALB/c‐nu mice." (PMID 36708044, 2023). "Our data supports our hypothesis that glioneuronal tumor CD34+ cells represent neuroectoderm neural precursor-like tumor precursor cells." (PMID 36966348, 2023). "By immunohistochemistry, tumor cells were positive for desmin, estrogen receptor, and CD34." (PMID 37662492, 2023). "In the viable areas triple fluorescence staining showed, next to inhibition of angiogenesis (CD31/CD34) and proliferation of both tumor- and endothelial cells (Ki-67), a marked increase of the number of infiltrating leukocytes (CD45), which suggests a correlation with induction of necrosis." (PMID 36459240, 2023). "Thus, the rapid tumor vasculature construction well adopted CD34+ budding endothelial cells leading to swift extension of the existing liver vessels into and around the growing tumor." (PMID 36781833, 2023). "The CD34 antibody was used to detect the density of tumor vessels." (PMID 37046045, 2023). "Considering their CD34 expression, we speculated that the tumor cells originated from primitive or naive hematopoietic cells." (PMID 36871023, 2023). "However, in the current study, we found that 25% of the KS tumor cells were co-expressing CD34 and Prox-1 which implies two scenarios that cannot, at this time, be distinguished." (PMID 37046832, 2023). "The tumor cells are diffusely and strongly positive for CD34 protein expression." (PMID 36672995, 2023). "The IHC results showed that the tumor cells were mottled and positive for CD34." (PMID 37454137, 2023). "For Avastin and sorafenib weak reactivity for CD34 was observed in cirrhotic and tumor nodules." (PMID 36874031, 2023). "Therefore, in this study we investigated IEPA’s mode of action and effects on multiple levels of cellular function in HNSCC (FaDu) and GBM (A172) tumor cells as well as in CD34+ HSPCs." (PMID 36903253, 2023). "ISH revealed positive Pol/Gag mRNA signals in CD34 + tumor cells from HIV + patients (95.8%)." (PMID 36316837, 2022). "Thus, immunofluorescence labeling of CD34 and αSMA in confocal microscopy has revealed co-location of both markers in some SCs in this type of angiogenesis during granulation tissue and tumor stroma formation." (PMID 36012273, 2022). "Our findings that both KSHV and HIV + CD34 + tumor cells prompted 2 further conjectures: HIV in KS directly promotes the carcinogenesis of KSHV or KSHV facilitates the mechanism of HIV entry into CD34 + tumor cells." (PMID 36316837, 2022). "Among 19 tumor-bearing β-cateninlox(ex3)/+ mice, three had benign neoplasms, eight had malignant ones, and the remaining eight mice had both types of tumors according to hematoxylin-eosin (H&E), reticular fiber, and CD34 stainings." (PMID 36122209, 2022). "Histological analysis further indicates that V+E@Gel could effectively inhibit tumor angiogenesis and metastasis by down-regulating the expression of CD34, CD31, MTA1 and TGF-β." (PMID 36145556, 2022). "Moreover, the low expression of adhesion molecules including ICAM-1 and 2, VCAM-1 and CD34 in tumor endothelial cells (EC) inhibit the effector T-cell from adhering to the EC and being transported to the tumor." (PMID 35401561, 2022). "The patchy or widespread tumor cell expression of CD34 was demonstrated in all cases." (PMID 35372027, 2022).
tumor (continued). "Culture in bioreactor of fresh tissue explants (organotypic culture) allows assessment of the dynamic evolution of tumor angiogenesis through serial sampling followed by histological and image analysis of tumor features (e.g., nuclei, stroma and angiogenic CD34+ vessels)." (PMID 35892706, 2022). "In addition to the lymphoid lineage markers including CD3, CD4, CD8, CD20, CD45, CD56, and FOXP3, we also examined myeloid lineage markers such as CD14, CD68, CD34 to accurately identify the specific cell types within the tumor microenvironment of YTMA-76." (PMID 35810563, 2022). "Moreover, Ki-67, a proliferation marker for human tumor cells, were also examined, as well as CD34 expression in cases of suspected CTCN." (PMID 35454875, 2022). "Differentiation and maturation of the majority of T cells into CD45RO-expressing effector memory and central memory T cells showed that allogeneic CD34+-derived progenitor cells underwent positive selection in the mouse thymus, which is pivotal for the generation of tumor-specific T cells." (PMID 35804867, 2022). "We demonstrated that HIV could infect CD34 + tumor cells and coexist with KSHV in KS, constituting a novel finding." (PMID 36316837, 2022). "In GBM, CD34 has been found to be expressed in the tumor vascular endothelial cell membrane." (PMID 35562993, 2022). "For deeper understanding of Siah2 role in ICC tumor immune microenvironment, we used CD34+ humanized NCG mice models, which have the same composition of immune cell subsets, especially regarding myeloid cells, which are considered to be a better preclinical model." (PMID 35154166, 2022). "Immunostains showed the tumor cells to be diffusely positive for CD34." (PMID 36276087, 2022). "Hoechst 33258 and CD34 marked the nucleus and the tumor blood vessels, respectively." (PMID 36164346, 2022). "IHC results also validated that linc00958 downregulation could inhibit the tumor microvessel density marker CD34 and VEGFA in tumors, supporting that the knockdown of linc00958 inhibited the angiogenesis in xenograft model." (PMID 36056431, 2022). "CD34 immunochemistry (IHC) staining was used to evaluate ACT tumor blood vessel density." (PMID 35628389, 2022). "This intra-tumor heterogeneity was more evident for some markers such as the cell adhesion molecule CD34 and the α3 and β1 integrins (CD49c and CD61 respectively) which were expressed only by highly restricted subpopulations of some PDHGG patient-derived cell lines." (PMID 36568177, 2022). "CD34 is the classical maker gene for tumor vessels; in addition, Cltc, Canx, and Ap2m1 were highly expressed in tumor vessels; these vessels could transport nanoparticles into tumor stroma." (PMID 36382024, 2022). "Meanwhile, we detected the expression levels of both Ki67 and CD34 using immunohistochemistry (IHC) and showed that the protein level of Ki67 and CD34 were significantly decreased in tumor cells transfected with Sja-miR-71a compared with that in the NC control." (PMID 35174106, 2022). "All four tumours were characterised by a remarkably strong extravascular CD34 positivity." (PMID 35836307, 2022). "A wide range of cytokines and chemokines, such as VEGF and SDF-1α, released by tumor microenvironment promote vasculogenesis and cancer progression by mobilization of BM resident CD34+ progenitors in the systemic circulation and enhancement of their recruitment to the tumor site." (PMID 36611906, 2022). "Interestingly, an analysis of surgical GBM specimens showed tumor vessels co-expressing markers of early vascular endothelial cells (CD34) and GSCs (ABCG2 and nestin), suggesting the existence of interim cells during the transdifferentiation process." (PMID 36294763, 2022). "Additionally, we also found a significant inverse correlation between CD34 positive capillaries and Ezrin expression in tumor tissue." (PMID 36142656, 2022). "As a vascular endothelial marker, CD34 is often used to mark tumour angiogenesis." (PMID 35501390, 2022).
tumor (continued). "Since it has been reported that TFPI2 may inhibit tumour metastasis by inhibiting the angiogenesis of tumour cells, we measured CD34 levels as well." (PMID 35501390, 2022). "Histological analysis further proved that V+E@Gel could effectively inhibit tumor angiogenesis and metastasis by down-regulating the expression of CD34, CD31, MTA1 and TGF-β." (PMID 36145556, 2022). "APC is a tumor suppressor gene that is known to affect Wnt/β-catenin signaling and CD34 expression." (PMID 35887203, 2022). "The tumor cells characteristically co-express CD34 and desmin." (PMID 36086676, 2022). "However, the potential for BMDCs to differentiate into CAFs (αSMA+) and TECs (CD34+) is highly variable and depends on tumor type, organ location, and tumor development stage." (PMID 34874922, 2022). "CD34+ cells formed the vessel loop structures in all tumor models." (PMID 34874922, 2022). "The CD34+ progenitor cell-mediated neovascularization process involves multiple steps, including BM cell mobilization, recruitment, and homing to neovessel sites, which are finely orchestrated by tumor cells." (PMID 36611906, 2022). "Additionally, we obtained paraffin-embedded specimens from the tumor to perform CD34, RANTES, and PD-L1 immunostaining." (PMID 35208526, 2022). "Additionally, we evaluated the expression of CD34, a transmembrane glycoprotein involved in the process of newly-forming tumour vessels by immunohistochemistry and immunofluorescence analysis." (PMID 34298658, 2021). "Tumor proliferation and angiogenesis were evaluated by Ki67 and CD34 staining respectively." (PMID 33685316, 2021). "Moreover, CD34 staining in the tumor indicated angiogenesis was suppressed by IPN and cisplatin-IPN treatment." (PMID 33685316, 2021). "In agreement to our tumor progression observation, in metastasis study, lung tumors sections showed the lower expression of cell proliferation marker Ki-67 and angiogenesis markers CD34 in p32-silenced B16F10 cells." (PMID 34711805, 2021). "Therefore, HE staining and the expression of PCNA and CD34 were used to evaluate the infiltration degree and proliferation rate of tumor cells in the peripheral soft tissue of puncture passage." (PMID 33743772, 2021). "Conversely, even though CD34+ CD38+ cell-surface antigen cells were highly detected in the tumor they couldn’t engraft new neoplasms." (PMID 34359786, 2021). "However, the expression of CD34 was significantly decreased in tumor tissues of both Hepa1-6 and HepG2 cells transfected with the sja-miR-61 mimics compared with the NC control, suggesting the inhibitory effect of sja-miR-61 on angiogenesis in the tumor." (PMID 34221971, 2021). "Fluorescence-activated cell sorting was used to enrich CD34+/CD45- CCSC from tumor biopsies." (PMID 34026616, 2021). "Additionally, expression of human-derived CD34 gradually decreased, implying that human stromal elements can change as the engrafted tumors settle into their new tumor microenvironment." (PMID 34327143, 2021). "The second proposed mechanism is that CD34 suppresses tumor development, in which case our data could provide a basis for the development of novel therapeutic agents." (PMID 34326362, 2021). "Tumor cells demonstrated positive IHC expression for CD34, CD31 and ERG IHC stains." (PMID 33593408, 2021). "IHC was carried out to detect DNMT1, TRAF1, p65, VEGF and CD34 in tumor tissues." (PMID 34749775, 2021). "Furthermore, the capillary density in the tumor was measured using anti-CD34 and anti-α-SMA immunohistochemical staining." (PMID 34109110, 2021). "MVD of the CD34(+) vessels correlated with tumor volume in the DLM group (p = 0.042, r = 0.89)." (PMID 34942951, 2021).
tumor (continued). "Furthermore, mice treated with CD3+CD34+ cells transduced following IL-7 culture had lower tumor volumes when compared to those treated with activated CD3+CD34+ cells (p = 0.0480)." (PMID 34172810, 2021). "These tumors are DFSP and superficial CD34 positive fibroblastic tumor (SCD34PFD)." (PMID 33879215, 2021). "Moreover, MPP also correlates inversely with tumor CD34 expression which is a marker of angiogenesis expressed both on hematopoietic and somatic cells." (PMID 33758304, 2021). "While the CD34 (endothelial neo-angiogenesis marker) expression increased with tumor progression (PCC +1.8-fold, p= 0.0003; advanced PCC +3.3-fold, p = 0.004), Vegfa was elevated only in advanced PCCs (+2.4-fold, p = 0.0121) and Angpt2 only in early-stage PCCs (+5.2-fold, p = 0.0003)." (PMID 33401758, 2021). "This suggests that the high expression of CD34/CD276 may promote a more complex tumor extracellular microenvironment, thus promoting the immune escape of CRC, which is consistent with the best KEGG pathway for GSEA enrichment analysis." (PMID 34307389, 2021). "In recent years, some studies have pointed out that immunohistochemical analysis showed that not only CD34 and Bcl2 are positive in tumor cells, but also nuclear STAT6 is positive, indicating that the tumor may be a rare variant of SFT." (PMID 33499815, 2021). "Blood may flow from tumor vessels that express CD34 to sinusoids, leading to blood clotting, the extension of blood lakes and sinusoids, and, sometimes, hemorrhagic necrosis." (PMID 33801639, 2021). "The combination of PCNA and CD34 can reflect the proliferation of tumor." (PMID 33743772, 2021). "Flow cytometric analysis for CD26 (Dpp4) and CD34 expression confirmed that iCAFs represent a substantial fraction of the EYFP+ PDPN+ tumor fibroblasts and that the subsets of Ly6C+ CD34+ and Sca-1+ CD34+ fibroblasts were significantly expanded after artLCMV treatment." (PMID 34354077, 2021). "Importantly, this schistosome miRNA exert a notable anti-angiogenesis activity as the expression of the angiogenesis marker (CD34) was significantly decreased in tumor tissues." (PMID 34221971, 2021). "Findings, including coexpression of markers supporting the transformation of CD34+SCs into αSMA+ stromal cells, could be more easily observable in these tumours with both types of stromal cells around the nest and strands of neoplastic cells." (PMID 33916213, 2021). "Tumor cells demonstrate positivity for CD34, Desmin and ASMA IHC stains." (PMID 33879215, 2021). "The tumor cells were positive for CD34, which is usually the case for DFSPs." (PMID 33803146, 2021). "In addition, the tumor cells were also positive for CD34, a marker present on both hematopoietic stem cells and HPCs." (PMID 34797454, 2021). "Lastly, CD34+ is an important tumor marker for potential wound healing." (PMID 34943815, 2021). "In immunohistochemical analysis, tumor cells were stained for CD34, CD99, and Bcl2." (PMID 33567630, 2021). "Since EET could produce the endothelial-like phenotype of tumour cells and promote the formation of VM to enhance the blood supply, VM formation was assayed by CD34-periodic acid-Schiff (PAS) double staining." (PMID 33685511, 2021). "Moreover, the number of CD34+α-SMA+ arteries in the tumor area were more than in the contralateral area." (PMID 35083148, 2021). "Nevertheless, PDX-cell enrichment rates would still be sufficient for diagnostic tumor cell analysis with acceptable loss of CD34+ cells, especially when considering that only a small fraction of the PBPC product needs to be processed for tumor cell diagnostics." (PMID 34654486, 2021). "We used CD34 to label vascular endothelial cells to assess tumor angiogenesis." (PMID 33442403, 2021). "We hypothesized that with these properties, CD34 might also be a suitable marker to evaluate the contribution of VW-SPCs to the vascularization of human tumor tissues in situ." (PMID 34359889, 2021).